PIK3CA (phosphatidylinositol-4,5-bisphosphate 3-kinase catalytic subunit alpha)
Diseases named in the same sentence as PIK3CA in open-access papers (continued):
Sharing a sentence is not in itself a finding about the gene and the disease.
breast cancer (continued). "Pooled ORR demonstrated that PI3K inhibitors generated 1.98 [95% CI, 1.46 to 2.70] odds ratio (OR) in HR+/PIK3CA-mutated breast cancer patients and 1.09 [95% CI, 0.78 to 1.53] odds ratio (OR) in HR+/PIK3CA wild-type breast cancer patients." (PMID 32461963, 2020). "Plenty of gene mutations, such as PIK3CA mutations, often occurred in HR+ breast cancer and associated with the clinical efficacy of therapeutic strategies." (PMID 32461963, 2020). "PIK3CA pathway is one of the most frequently deregulated pathways in breast cancer and has been implicated in breast tumor development, progression and therapeutic resistance." (PMID 32695676, 2020). "The frequency of PIK3CA mutations in breast cancer has also attracted attention as a potential drug target." (PMID 32695676, 2020). "It was previously reported that CDK4/6 inhibitors activated the PI3K/AKT pathway through the phosphorylation of S473/T308 on AKT and CDK4/6 and PI3K inhibitor combination reduced AKT phosphorylation in PIK3CA mutated breast cancer cell lines." (PMID 32899250, 2020). "H1047R and E545K are major mutations in PIK3CA and are often found in cancer patients, including breast cancer patients." (PMID 32640677, 2020). "GDC-0032 (taselisib) has greater selectivity for mutant PI3Kα isoforms and is effective in inhibiting proliferation of p110α-mutant breast cancer cell lines in vitro and the growth of human breast cancer xenograft models harboring PIK3CA mutations in vivo." (PMID 32976773, 2020). "This makes them powerful diagnostic tools for breast cancer, especially for PIK3CA protein, and methylated 14-3-3 σ promoter as the evidence is based on meta-analyses." (PMID 32118013, 2020). "Prevalence of this mutation and utility of test methodologies likely warrants PIK3CA mutation testing in all patients with this breast cancer subtype via definitive assessment of PIK3CA mutational status." (PMID 32637176, 2020). "We have well-demonstrated the favorable role of PIK3CA mutations for PI3K inhibitors in HR+ breast cancer therapy, whereas our study still has some limitations that should be concerned." (PMID 32461963, 2020). "Specifically, the I391M mutation of PIK3CA has been reported in prostate cancer, breast cancer and melanoma." (PMID 33748184, 2020). "The SOLAR-1 trial studied the effects of alpelisib therapy on progression-free survival of patients with HR+, HER2−, PIK3CA mutated, advanced breast cancer who had received endocrine therapy in the past." (PMID 32542231, 2020). "This is comparable to what is observed in breast cancer, in which activating PIK3CA mutations are reported in 25–38% of HER2-positive breast cancers." (PMID 33375706, 2020). "A phase II monotherapy study in patients with advanced breast cancers with PIK3CA or Akt mutations showed very limited clinical activity." (PMID 32774769, 2020). "In conclusion, male breast cancers constitute a heterogeneous disease, with a limited number of recurrently mutated genes (PIK3CA, GATA3, and MAP3K1) and numerous genes with pathogenic mutations at lower frequencies." (PMID 32210163, 2020). "Patients #1, #4, #5, #7 and #9 presented with a breast cancer with homogeneous presence of a PIK3CA mutation in each individual tumour component, whereas PIK3CA mutations were heterogeneously distributed in the tumours of patients #3 and #6." (PMID 32058674, 2020). "BYL719 is a selective inhibitor for p110α which has been approved to treat PIK3CA-mutated breast cancer." (PMID 32632138, 2020).
breast cancer (continued). "Among the most frequent causes is constitutive signaling through mutational activation of phosphatidylinositol-4,5-bisphosphate 3-kinase catalytic subunit alpha (PIK3CA), which is mutated in 45% of luminal breast cancers." (PMID 32850327, 2020). "In luminal breast cancer, incidence of PIK3CA mutations is about 30% in primary tumors and metastases." (PMID 32325878, 2020). "A recent study suggested PIK3CA mutations to be a major mediator of therapy resistance in breast cancer." (PMID 31980592, 2020). "PIK3CA H1047R is most commonly found in breast cancer and is also frequently mutated among multiple tumor types in the MSK-IMPACT metastatic cancers." (PMID 32733937, 2020). "The ability of PIK3CA mutation status to predict the benefit of PI3K inhibitors is imperative for further subclassification of HR+ breast cancer." (PMID 32461963, 2020). "Breast cancers with PIK3CA mutations can be treated with PIK3CA inhibitors in hormone receptor-positive HER2 negative subtypes." (PMID 33166334, 2020). "Mutations in AURKA and PIK3CA have previously been shown to be significantly associated with breast cancer survival rates." (PMID 32079541, 2020). "Loss of the tumor suppressor PTEN led to resistance to the PI3Kα inhibitor BYL-719 (alpelisib) in a breast cancer patient with metastatic breast cancer bearing an activating PIK3CA-mutation." (PMID 32976773, 2020). "These preclinical findings support the therapeutic potential of combination treatment with an AKT inhibitor and HER2 therapies in patients with HER2+ breast cancer carrying PIK3CA mutations." (PMID 33303839, 2020). "Compared with the Chinese patients, the frequency of actionable PIK3CA mutations was increased in both primary and advanced breast cancers in the Western patients in the MSKCC dataset according to the OncoKB criteria." (PMID 33173047, 2020). "In this study, we assessed time to metastasis and survival according to use of medications between time of diagnosis and metastasis and PIK3CA tumor mutation status among women with HR+/HER2- breast cancer that had metastasized." (PMID 32326897, 2020). "For example, the identification of the PIK3CA gene mutation makes it possible to identify a special group of patients (PIK3CA-positive breast cancer) who receive the greatest benefit from molecular-targeted anti-PI3K therapy." (PMID 33287350, 2020). "Expression of mutant PIK3CA or loss of PTEN in breast cancer cell lines is associated with resistance to HER2-targeted therapies." (PMID 31462705, 2020). "The study reported 10% frequency of PIK3CA somatic mutations in breast cancer, but later studies reported ∼30%." (PMID 33375317, 2020). "The overall frequency of PIK3CA mutations in breast cancers has been reported as 20–40% and they are more prevalent in HR-positive and HER2-positive breast cancers than in triple-negative breast cancers." (PMID 32176735, 2020). "Mutations in PIK3CA have been reported in 20%‐40% of breast cancer cases, and their incidence also varies across different breast cancer molecular subtypes." (PMID 32697890, 2020). "The prevalence of alpelisib on/off-label PIK3CA mutations was similar across breast cancer subtypes, with the lowest frequency seen in TNBC." (PMID 32983983, 2020). "PIK3CA, encoding the PI3Kα isoform, is the most frequently mutated oncogene in estrogen receptor (ER)-positive breast cancer." (PMID 32976773, 2020). "The concordance of PIK3CA mutations is demonstrated in tumor and plasma samples in breast cancer that have been found to be elevated in both." (PMID 32629823, 2020). "In this preclinical study, we investigated combination therapy with small-molecule inhibitors of AKT and HER2 to overcome limitations associated with anti-HER2 monotherapy in HER2+ breast cancer cell lines with PIK3CA mutations." (PMID 33303839, 2020).
breast cancer (continued). "Strikingly, only 4.4% of M0-stage patients harbored PIK3CA mutations, whereas manifest HR+ breast cancer patients with metastasis displayed them in 34.3% of cases (Fisher’s exact test, p < 0.0001)." (PMID 33020483, 2020). "PIK3CA is the most common somatic mutation identified in breast cancer to date, with prevalence of 25–40% in most studies." (PMID 32326897, 2020). "For example, PIK3CA mutation is most frequently seen (nearly 50%) in aggressive breast cancers that display EMT and CSC properties." (PMID 31600013, 2020). "Regarding gene alterations as well as the upregulation of ABL-1 in BM and downregulation of PIK3CA in metastatic breast cancer cells, BRAF mutations in melanoma and EGFR and KRAS overexpressions in lung cancer have been reported." (PMID 31900168, 2020). "These advancements demonstrated a quick, accurate and simple detection and quantitation of PIK3CA mutations in two breast cancer cohorts (first cohort n = 22, second cohort n = 25)." (PMID 33051521, 2020). "A total of 6 studies provided data about the progression-free survival (PFS) of PI3K inhibitors in HR+ breast cancer according to PIK3CA mutation status." (PMID 32461963, 2020). "Among the actionable mutations, PIK3CA were found not only in the very well known breast cancers but in a number of other cancers from like uterine carcinoma, Sezary syndrome, oral cancers, and glioblastoma, with the exception of lung." (PMID 31991072, 2020). "Among these oncogenic alternations, PIK3CA mutations are observed in approximately 20–30% of patients with breast cancer, and cause resistance to anti-HER2 therapies in both preclinical and clinical settings." (PMID 33303839, 2020). "One study found a 41.1% frequency of PIK3CA mutation in HR+/HER2- breast cancer compared to 12.5% of patients with triple negative breast cancer." (PMID 32637176, 2020). "In this study, we report two novel primer sets using an allele-specific LAMP assay to detect the missense p.H1047R, PIK3CA somatic mutation, which is a common driver mutation in breast cancer." (PMID 32165708, 2020). "For example, alpelisib is an α-specific PI3K inhibitor that has shown great promise in the treatment of advanced breast cancer containing a PIK3CA mutation." (PMID 32542231, 2020). "The predictive and prognostic role of PIK3CA mutations will facilitate the diagnosis and prognosis of HR+ breast cancer." (PMID 32461963, 2020). "In most double-PIK3CA-mutant breast cancers, one of the mutations was either a helical or kinase domain major-hotspot mutation." (PMID 32210163, 2020). "In one breast cancer patient with radiologically and clinically suspected LM, cfDNA showed a targetable PIK3CA mutation." (PMID 31903155, 2020). "PIK3CA mutation, which leads to increased PI3K activity, is the most common somatic mutation in breast cancer, and 36% of patients with HR+/HER2- breast cancer are PIK3CA mutated." (PMID 33489906, 2020). "In a query of The Cancer Genome Atlas (TCGA) database, we found that PIK3CA was the most frequently mutated gene in breast cancer, while MYC and CDKN2A/B were the genes most frequently associated with amplifications and deletions, respectively." (PMID 32498332, 2020). "PIK3CA E545K is a hotspot mutation in breast cancer and has corresponding first-line drugs (Alpelisib and Fulvestrant)." (PMID 32733937, 2020). "Further, PRR11 amplifications were mutually exclusive of PIK3CA mutations in genomic breast cancer databases." (PMID 33127913, 2020).
breast cancer (continued). "Data from 10 319 early breast cancer patients with known PIK3CA genotype showed that PIK3CA mutations were associated with better invasive DFS, distant DFS, and OS." (PMID 32697890, 2020). "Alpelisib, a PI3K inhibitor, has been recently approved by the FDA for advanced or metastatic HER2-negative, hormone receptor positive with PIK3CA-mutation, that exhibits progression to endocrine therapy in breast cancer." (PMID 32391269, 2020). "Mutations in PIK3CA are among the most frequent in solid tumors, and especially in estrogen receptor (ER)-positive breast cancer." (PMID 32976773, 2020). "PIK3CA mutant breast cancer cell lines, with additional mutations in KRAS, are shown to confer resistance to inhibition by AZD8835." (PMID 32194423, 2020). "The Lotus trial showed that ipatasertib, an oral AKT inhibitor, improved the progression-free survival of breast cancer patients with PIK3CA/AKT/PTEN mutations." (PMID 33004031, 2020). "Previous studies in our laboratory have demonstrated that inhibitors of the PI3K/AKT/mTOR pathway have selective activity in ER+ breast cancer cell lines carrying activating mutations in PIK3CA." (PMID 32795346, 2020). "Approximately 30–40% of patients with breast cancer present PIK3CA mutations, which will induce hyperactivation of the α isoform (p110α) of PI3K." (PMID 33375317, 2020). "In patients with early-stage breast cancer, PIK3CA mutations have been identified presurgically in ctDNA with high sensitivity (93.3%) and specificity (100%)." (PMID 32010431, 2020). "Network meta-analysis included all interventions for ORR, and all interventions for 6m-PFS were presented as network plots in the PIK3CA-mutated subgroup and the PIK3CA-mutated and wild-type total subgroup patients with breast cancer." (PMID 33376736, 2020). "The American Food and Drug Administration recently approved this treatment in combination with fulvestrant in metastatic settings for hormone receptor-positive, PIK3CA-mutated breast cancer." (PMID 32087759, 2020). "Other preclinical studies also reported the efficacy of taselisib in cellular models with mutations in PIK3CA in breast cancer." (PMID 32211045, 2020). "PIK3CA mutations played important roles in resistance to single-agent anti-HER2 therapy in breast cancer cell lines." (PMID 33303839, 2020). "PIK3CA is one of the two most frequently mutated genes in breast cancers, occurring in 30–40% of cases." (PMID 33051521, 2020). "Our findings support the value of somatic PIK3CA mutations as predictive biomarker for PI3K‐targeting therapies combined with antihormonal treatment in metastatic HR+ breast cancer." (PMID 32352244, 2020). "Mutations in PIK3CA were most frequently identified in breast cancers and lung cancers, while BRAF mutations were most frequently identified in colorectal cancers and melanomas." (PMID 32087721, 2020). "PIK3CA mutation rate in HER2-positive breast cancers is about 23%, and patients with PIK3CA mutations have a lower pCR rate after HER2-targeted NACT." (PMID 32638235, 2020). "This phase II study evaluated the efficacy and safety of buparlisib plus tamoxifen in pretreated patients with advanced HR+/HER2− breast cancer, stratified for PIK3CA mutations and/or loss of PTEN expression in tumor tissue and circulating blood DNA." (PMID 32352244, 2020).
breast cancer (continued). "Both technologies have been shown to be able to detect PIK3CA mutations in plasma ctDNA from breast cancer patients." (PMID 33322643, 2020). "MpBC tumors harbor more PIK3CA mutations than hormone receptor (HR)+ breast cancers, in which 36.4% of those cancers have a PIK3CA mutation." (PMID 33148288, 2020). "Alpelisib, the first PI3K inhibitor approved by the FDA, is approved to treat breast cancer patients with PIK3CA-mutation." (PMID 33004905, 2020). "Drawing on advances in nuclease mediated enrichment, we describe here an enrichment method for the 4 most common PIK3CA mutant alleles, and their detection with PCR-based techniques both from breast cancer tissue and from cfDNA samples." (PMID 33051521, 2020). "In patients with HER2-positive breast cancer, PIK3CA mutations reportedly confer resistance to trastuzumab, a monoclonal antibody targeting HER222." (PMID 32296588, 2020). "In early‐stage breast cancer, PIK3CA mutations have been associated with slightly better 5‐year OS than PIK3CA‐wt tumors in univariable analysis, but not when correcting for clinicopathological and treatment variables." (PMID 32926574, 2020). "Several ctDNA-based companion diagnostic tests have now received United States Food and Drug Administration (FDA) approval, including for the detection of PIK3CA mutations in breast cancer." (PMID 33001984, 2020). "Recently, the FDA (Food and Drug Administration) approved testing of breast cancer patients with PIK3CA mutations using breast tumor tissue and/or circulating tumor DNA, isolated from plasma specimens." (PMID 33375317, 2020). "Aberrant mutation of PIK3CA (which encodes the p110α subunit of PI3K) is found in 40% of estrogen receptor (ER)-positive breast cancers (BrCas)." (PMID 33024087, 2020). "Genetic analysis of DCCs revealed that DCCs from HR+ breast cancer progressing to manifest metastasis often acquired PIK3CA mutations, possibly because the activated PI3K/AKT pathway rendered mammary epithelial cells independent of IL-6 trans-signaling." (PMID 33020483, 2020). "With mutation-matching therapy now approved in breast cancer, with alpelisib for PIK3CA-mutant disease, ctDNA testing can be seen as a standard-of-care test for both common and rare targetable genetic events." (PMID 32919527, 2020). "Further, we did not identify any likely driver mutations in the top 20 most frequently mutated genes in human breast cancer, with the exception of Pik3ca, which was mutated in one of the recurrent tumor cell lines." (PMID 33024122, 2020). "PIK3CA is mutated in approximately 35% of all breast cancers and is more frequent in ER-positive BC." (PMID 33376736, 2020). "PIK3CA mutations are particularly frequent in HR+ breast carcinomas and potent drivers of carcinogenesis through AKT activation, evasion of apoptosis, and promotion of invasion." (PMID 32377505, 2020). "Most luminal breast carcinomas (BrCas) bearing PIK3CA mutations initially respond to phosphoinositide-3-kinase (PI3K)-α inhibitors, but many eventually become resistant." (PMID 33024087, 2020). "PIK3CA is the most frequently mutated gene found in breast cancer, and it is an integral component of the phosphatidylinositol 3 kinase (PI3K) signaling pathway." (PMID 30682127, 2019). "PIK3CA is the most commonly mutated oncogene in Thai TNBC cohort similar to other breast cancer studies." (PMID 30828495, 2019). "In the context of breast cancer, PIK3CA mutations have been observed in each of the different subtypes, but mostly in hormone receptor-positive tumors where it’s associated with disease progression and resistance to endocrine therapy." (PMID 32355893, 2019).